POLB (DNA polymerase beta)
Description:
Repair polymerase that plays a key role in base-excision repair. During this process, the damaged base is excised by specific DNA glycosylases, the DNA backbone is nicked at the abasic site by an apurinic/apyrimidic (AP) endonuclease, and POLB removes 5'-deoxyribose-phosphate from the preincised AP site acting as a 5'-deoxyribose-phosphate lyase (5'-dRP lyase); through its DNA polymerase activity, it adds one nucleotide to the 3' end of the arising single-nucleotide gap. Conducts 'gap-filling' DNA synthesis in a stepwise distributive fashion rather than in a processive fashion as for other DNA polymerases. It is also able to cleave sugar-phosphate bonds 3' to an intact AP site, acting as an AP lyase.
Tractability: Small molecule: a structure with a bound ligand is known; a high-quality ligand is known; it has a binding pocket of medium quality; it belongs to a druggable protein family. PROTAC: UniProt records ubiquitination sites on it; ubiquitination databases record sites on it; its protein half-life has been measured; a small molecule that binds it is known.
Target class: Enzyme
Gene: Protein-coding gene on chromosome 8 (42,338,454 to 42,371,808, forward strand). Ensembl gene ENSG00000070501.
Subcellular location: Nucleus; Cytoplasm
Subcellular location (Human Protein Atlas): Cytosol; Vesicles
Pathways (Reactome):
DNA Repair: APEX1-Independent Resolution of AP Sites via the Single Nucleotide Replacement Pathway; Abasic sugar-phosphate removal via the single-nucleotide replacement pathway; PCNA-Dependent Long Patch Base Excision Repair; POLB-Dependent Long Patch Base Excision Repair; Resolution of AP sites via the multiple-nucleotide patch replacement pathway; Resolution of AP sites via the single-nucleotide replacement pathway
Metabolism of proteins: Ub-specific processing proteases
Gene Ontology:
Molecular function: 5'-deoxyribose-5-phosphate lyase activity; class I DNA-(apurinic or apyrimidinic site) endonuclease activity; DNA-directed DNA polymerase activity; enzyme binding; lyase activity; microtubule binding; protein binding; DNA-(apurinic or apyrimidinic site) endonuclease activity; damaged DNA binding; DNA binding; DNA polymerase activity; metal ion binding; nucleotidyltransferase activity
Biological process: base-excision repair; DNA damage response; nucleotide-excision repair, DNA gap filling; base-excision repair, gap-filling; DNA repair; DNA-templated DNA replication; regulation of DNA repair; DNA biosynthetic process; pyrimidine dimer repair; response to ethanol; response to gamma radiation; response to hyperoxia
Cellular component: cytoplasm; cytosol; microtubule; nucleus; protein-containing complex; spindle microtubule; DNA ligase III-XRCC1 complex; nucleoplasm; site of DNA damage
Genetic constraint (gnomAD): Loss-of-function variants: 4 observed, 4.47 expected, observed/expected ratio (o/e) 0.89, 90% interval 0.43 to 1.77. That is too few expected variants to judge how well the gene tolerates losing a copy. Missense variants: 38 observed, 51.26 expected, observed/expected ratio (o/e) 0.74, 90% interval 0.57 to 0.97. Synonymous variants: 17 observed, 19.95 expected, observed/expected ratio (o/e) 0.85, 90% interval 0.58 to 1.28.
Homologues: Orthologues: chimpanzee POLB (100% identical), macaque POLB (99% identical), dog POLB (99% identical), mouse Polb (96% identical), rat Polb (96% identical), guinea pig POLB (96% identical), pig POLB (91% identical), rabbit POLB (88% identical), tropical clawed frog polb (84% identical), zebrafish polb (80% identical). Paralogues in human: POLL (36% identical), POLM (24% identical), DNTT (23% identical).
Diseases named in the same sentence as POLB in open-access papers:
POLB is named in the same sentence as 39 diseases in open-access papers, as found by Europe PMC text mining. Sharing a sentence is not in itself a finding about the gene and the disease. The quoted sentences say what the papers report.
lupus (6 papers, 2015 to 2024). "For example, studies on a POLB mouse model with decreased efficiency suggest a link to lupus symptoms, potentially due to heightened NETosis resulting from the PolB mutation, along with other variations in repair proteins and enzymes." (PMID 39456240, 2024). "It is possible that the observed phenotype may be the result of excess NETosis (which have been implicated in Lupus) as a result of the mutation in PolB, and other repair proteins and enzymes." (PMID 36426351, 2022). "For instance, a POLB mouse model where PolB is less efficient has been reported to exhibit lupus symptoms." (PMID 36426351, 2022). "Mice carrying the Y265C hypomorphic allele of POLB (DNA polymerase, beta; a key enzyme in BER mechanism) demonstrated several pathologies resembling lupus, such as nephritis and skin manifestations, along with high titers of anti-nuclear antibodies in serum." (PMID 31861764, 2019). "To determine if the hematopoietic compartment is sufficient for development of lupus, we transplanted bone marrow cells isolated either from the POLBY265C/C or POLB+/+ mice into “Pep Boy” congenic recipients." (PMID 35486639, 2022). "To address whether the hematopoietic compartment is sufficient for lupus development, we transplanted bone marrow cells from POLBY265C/C and POLB+/+ into wild-type congenic mice." (PMID 35486639, 2022).
breast carcinoma (5 papers, 2012 to 2024). "POLB, as a core component of BER system, has been shown to exert demethylation abilities closely associated with lung and breast cancer metastasis." (PMID 38245510, 2024). "On one hand, the expression levels of POLB have been found to be elevated in certain tumors, including lung cancer, breast cancer, and colon cancer." (PMID 38245510, 2024). "Overexpression of POLB decreases the metastasis and invasion of lung and breast cancers." (PMID 38245510, 2024).
colon carcinoma (5 papers, 2016 to 2024). "Of the many mutations recently identified in a large cohort of colon cancer patients, as many as 75% of the tumors presented with POLB gene mutations." (PMID 31287140, 2019). "To that end, we used a human colon tumor-derived cell line (HCT116) with a CRISPR/Cas9-mediated mutation in the first exon of POLB to test whether knockout (KO) of this DNA repair gene influenced the level of DNA damage in HCT116 cells, with or without previous exposure to genotoxicants." (PMID 29426857, 2018). "HTLV-1 Tax acts on genes indirectly by binding several TFs, such as TCF3, ELK1, and MYC in colon cancer, as well as POLB, BUB3, and CDK4, according to the HTLV-1 infection signaling pathway." (PMID 39228892, 2024). "The present paper examines the impact of polymorphisms of PolB, LIG3, and EXO1 of the BER repair system on the modulation of the risk of colon cancer." (PMID 26649135, 2016).
gastric cancer (5 papers, 2015 to 2025). A primary or metastatic malignant neoplasm involving the stomach. "High levels of POLB are closely associated with tumor metastasis and poor prognosis in other malignancies, such as esophageal cancer and gastric cancer." (PMID 33673690, 2021). "Previous studies have shown a correlation between single nucleotide polymorphisms (SNPs) of the POLB gene and the risk to develop various cancers, including gastric cancer." (PMID 26090616, 2015). "L22P was discovered as a gastric cancer-associated variant of POLB." (PMID 41568291, 2025). "POLB mutations were reported to be positively associated with PR expression in gastric cancer." (PMID 35494043, 2022). "In this study, we examined whether reduced BER capacity associated with mutation in the POLB gene, along with increased DNA damage generated by H. pylori infection, accelerates gastric cancer development." (PMID 31216714, 2019). "Based on our previously published data and the current recent findings, POLB status of the patient likely provide genetic indicators to stratify gastric cancer patient." (PMID 41568291, 2025). "Mutation in DNA polymerase beta (Pol β) impacts BER efficiency and has been reported in approximately 30–40% of gastric carcinoma tumors." (PMID 31216714, 2019). "Our observation may imply that gastric cancer patients carrying defects in POLB function may be stratified for PARP1 inhibitor treatment, resulting in a more effective option." (PMID 26090616, 2015). "Therefore, we extended our study using the POLB mutant mouse model to examine whether H. pylori infection could affect the incidence of gastric cancer in this model." (PMID 31216714, 2019).
autoimmune disease (2 papers, 2020 to 2022). A disorder resulting from loss of function or tissue destruction of an organ or multiple organs, arising from humoral or cellular immune responses of the individual to their own tissue constituents. "A recent publication has shown that POLB deficiency triggers cytosolic DNA mediated cGAS-STING signaling pathway activation in immune cells with autoimmune disease." (PMID 36624848, 2022). "Finally, it was hypothesized that the increased turnover and apoptosis in GCs in hypomorphic POLB mice increases the exposure to self-antigen, causing autoimmune disease." (PMID 32547565, 2020). "There is a potential link between POLB and autoimmune diseases." (PMID 32547565, 2020).
colorectal cancer (2 papers, 2012 to 2016). A primary or metastatic malignant neoplasm that affects the colon or rectum. "The simultaneous occurrence of the Lys/Glu genotype of the EXO1 gene and the Pro/Pro genotype of the PolB gene was found to possibly increase the risk of colorectal cancer (OR = 2.265 (1.193–4.301), p = 0.011)." (PMID 26649135, 2016). "POLB has been called the “platinum resistance gene” due to the fact that reduced POLB expression in colorectal cancer cells results in susceptibility to cisplatin." (PMID 22973298, 2012). "In addition, polymorphisms of EXO1, LIG3, and PolB may modulate the risk of colorectal cancer by decreasing (PolB) or increasing (LIG3 and EXO1) the chance of malignant transformation." (PMID 26649135, 2016).
esophageal cancer (2 papers, 2021 to 2024). A primary or metastatic malignant neoplasm involving the esophagus. "POLB, a repair polymerase essential for base-excision repair and linked to Werner syndrome and esophageal cancer, is consistently predicted across seeds as SL partner for POLB among the top 20 candidates." (PMID 39372928, 2024).
lung carcinoma (2 papers, 2022 to 2024). "The carrier status for the POLB rs3136797 germline mutation is associated with a worse prognosis for lung cancer and demonstrates poor sensitivity to cisplatin treatment." (PMID 35293140, 2022).
lymphoma (2 papers, 2020 to 2022). A malignant (clonal) proliferation of B- lymphocytes or T- lymphocytes which involves the lymph nodes, bone marrow and/or extranodal sites. "We speculate that the overall loss of POLB in combination with dUTP misincorporation related to DNA replication, and spontaneous base deaminations destabilize the genome in GC B cells, thereby potentially driving the development of GC B-cell derived lymphomas." (PMID 32547565, 2020). "Specificity of the POLB antibody used for immunohistochemistry was confirmed by immunoblotting and immunohistochemistry on paraffin-embedded CH12/F3 Polb knockdown mouse GC-derived lymphoma cells." (PMID 36700204, 2022).
acute lymphoblastic leukemia (1 paper, 2025). Leukemia with an acute onset, characterized by the presence of lymphoblasts in the bone marrow and the peripheral blood. "Some studies have shown that mismatch repair deficient acute lymphoblastic leukemia cells more dependent on POLB-mediated BER pathway to counteract the cytotoxic effects of thiopurine." (PMID 41568291, 2025).
Alzheimer disease (1 paper, 2015). A progressive, neurodegenerative disease characterized by loss of function and death of nerve cells in several areas of the brain leading to loss of cognitive function such as memory and language. "One study suggested that base excision repair was impaired in the brain tissues of Alzheimer's disease patients via dysfunction of DNA glycosylases and DNA polymerase beta." (PMID 25510912, 2015).
bladder cancer (1 paper, 2025). "This study identified five prognostic biomarker genes related to mitochondrial function and programmed cell death in bladder cancer (POLB, FASN, CASP9, VDAC2, and RHOT2) and preliminarily constructed a prognostic model based on these genes." (PMID 41427247, 2025). "Thus, in-depth exploration of the specific mechanisms of action of POLB in bladder cancer is of great significance for optimizing bladder cancer treatment strategies and identifying new targets to overcome resistance." (PMID 41427247, 2025). "In this study, a novel prognostic model for bladder cancer was constructed based on POLB, FASN, CASP9, VDAC2, and RHOT2, which provided preliminary references for the prognostic evaluation of bladder cancer and subsequent studies related to its diagnosis and treatment." (PMID 41427247, 2025).
Cervical lymphadenopathy (1 paper, 2017). Enlarged lymph nodes in the neck. "It was shown that mutant POLB (Y265C) repairs DNA significantly more slowly than do wild-type (WT) Pol β, and mutant POLB mice develop dermatitis, GN, cervical lymphadenopathy, and high titers of ANA, i.e., pathology resembling SLE." (PMID 27933432, 2017).
chronic lymphocytic leukemia (1 paper, 2025). "In chronic lymphocytic leukemia (CLL), Nrf2 activation can enhance the expression of DNA repair genes such as XRCC1 and POLB, which may contribute to disease progression and resistance to chemotherapy." (PMID 40422216, 2025).
chronic myeloid leukemia (1 paper, 2024). "Furthermore, research has shown that DNA polymerase beta (POLB) exhibits increased activity in chronic myeloid leukemia (CML)." (PMID 39768855, 2024).
esophageal squamous cell carcinoma (1 paper, 2024). Esophageal squamous cell carcinoma (ESCC) is a type of esophageal carcinoma (EC) that can affect any part of the esophagus, but is usually located in the upper or middle third. "Nevertheless, POLB knockdown induces cell cycle defects and enhances cell proliferation in mouse esophageal squamous cell carcinoma and human oral squamous cell carcinoma." (PMID 38731327, 2024).
liver cancer (1 paper, 2024). An epithelial or non-epithelial malignant neoplasm that arises from the liver. "Therefore, POLB is a bona fide oncogene involved in the pathogenesis of liver cancer." (PMID 38245510, 2024). "Therefore, at least in our study, POLB’s role in HCC progression is positive and it serves as a promising integrator linking the circadian clock signals to liver cancer development." (PMID 38245510, 2024).
lung adenocarcinoma (1 paper, 2016). A carcinoma that arises from the lung and is characterized by the presence of malignant glandular epithelial cells. "The interaction between EXOG with APE1, PolG or Lig3, but not between nuclear-specific DNA repair enzymes FEN1 and PolB, was markedly reduced by H2S biosynthesis inhibition in lung adenocarcinoma (but not in normal epithelial cells)." (PMID 27808278, 2016).
lupus like syndrome (1 paper, 2022). "This was experimentaly confirmed by mutation of POLB in mice that spontanously developed lupus like syndrome." (PMID 35048206, 2022).
oral cancer (1 paper, 2021). "In conclusion, we demonstrated that low expression of POLB was associated with advanced tumor stage and worse overall survival in patients with oral cancer." (PMID 33673690, 2021). "Given that the functional properties and morphology of oral cancer cells are affected by the presence of POLB, we further examined whether these changes could be correlated to cell-cycle regulation and chromosomal instability." (PMID 33673690, 2021).
oral cavity cancer (1 paper, 2021). A primary or metastatic malignant neoplasm involving the oral cavity. "Nevertheless, the precise role of POLB in oral cavity cancer is still unknown." (PMID 33673690, 2021). "Therefore, there is a strong connection between POLB and the occurrence of oral cavity cancer." (PMID 33673690, 2021). "To determine whether POLB is an important prognostic marker in OSCC patients, we used immunohistochemical staining to explore the relationships between POLB and clinicopathological parameters in biopsy specimens from 133 patients with oral cavity cancer." (PMID 33673690, 2021).
prostate carcinoma (1 paper, 2024). A carcinoma that arises from epithelial cells of the prostate gland. "On the other hand, POLB mutations with lower enzymatic activities have also been detected in most types of human cancers, including colorectal tumor, gastric carcinoma and prostate cancers." (PMID 38245510, 2024). "Of note, POLB is a core component in BER system, and inhibition of BER pathway has been proven to decrease the prostate cancer cell proliferation and is a potential therapeutic strategy for prostate cancer treatment." (PMID 38245510, 2024).
radicular cyst (1 paper, 2021). "For radicular cyst, POLB and PRKAG2 genes were identified with A>G (rs2272615) of 0.83 and C>T (rs7429) of 0.79 polymorphism percentage in other African and other Asian population, respectively." (PMID 34539639, 2021).
sarcoidosis (1 paper, 2022). Sarcoidosis is a multisystemic disorder of unknown cause characterized by the formation of immune granulomas in involved organs. "Two different clones (p51-BP4–457 and p51-BP3–57) with reduced expression in sarcoidosis had the same sequences with homology to POLB." (PMID 35048206, 2022).